BRAF (B-Raf proto-oncogene, serine/threonine kinase)
Diseases named in the same sentence as BRAF in open-access papers (continued):
Sharing a sentence is not in itself a finding about the gene and the disease.
melanoma (continued). "Furthermore, skin melanoma is characterized by frequent amplifications of BRAF (7q34), NRAS (1p13.2), KIT (4q11) oncogenes (major mutated genes in melanoma) but also by EGFR (7p11.2) and MET (7q31.2) genes." (PMID 34885093, 2021). "The current management of advanced-stage melanomas is greatly determined by the presence or absence of a mutation in this gene, as targeted therapy with BRAF kinase inhibitors is one of the first therapeutic choices for these patients." (PMID 33954019, 2021). "Interestingly, this effect was further facilitated when MAFs were cultured in the presence of BRAF inhibitor- or chemotherapy-treated cultured melanoma cells." (PMID 34944793, 2021). "Similarly, mutant BRAF in melanoma stimulates MAPK signaling and can result in expression of IL-6 and IL-10, promoting immune-tolerant DC maturation and inhibiting cytotoxic T cells." (PMID 35082797, 2021). "Another FGFRs inhibitor, LY2874455, re-sensitizes BRAF-mutant melanoma cells to vemurafenib." (PMID 34830951, 2021). "This interaction between SIRT3 and glutamine metabolism would be interesting to study in other cancers, such as melanoma, where inhibiting glutamine transport has been considered as a method of suppressing melanoma growth in both wild-type BRAF and BRAF-inhibitor-resistant melanoma." (PMID 34831420, 2021). "Eventually, stroma-mediated BRAF-independent resistant melanoma cells emerged." (PMID 34680395, 2021). "Together, the data indicate that PERK may help regulate resistance to BRAF inhibition in melanoma with impaired PTEN." (PMID 34282258, 2021). "Furthermore, it was described that melanoma cells resistant to BRAF inhibitors showed an oxidative metabolism that was more important and dependent on mitochondria for cell survival." (PMID 33431809, 2021). "Thus, there is an urgent unmet medical need to develop novel agents overcoming acquired BRAF inhibitor resistance in melanoma." (PMID 33917428, 2021). "First, we tested whether ASAH1 knockdown alters the sensitivity of BRAF-mutant melanoma cells to the BRAF kinase inhibitor vemurafenib in vitro." (PMID 33766731, 2021). "Previously, it has been shown that BRAF mutant colon cancer cell lines have higher levels of phospho-protein kinase B (AKT) indicative of an activation of the phosphoinositide 3-kinase (PI3K)–AKT pathway when compared to BRAF mutant melanoma." (PMID 34639107, 2021). "PAK1 is overexpressed in a subset of BRAF wildtype melanomas." (PMID 34827551, 2021). "This inhibitor exhibited a strong antitumor activity on BRAF(V600E)-harboring melanoma in vitro and in vivo, and its analog with more favorable pharmacokinetics, vemurafenib (PLX4032), was first approved for treating advance melanomas and then for other cancers with BRAF(V600E) mutation." (PMID 35582307, 2021). "Another study showed that long-term treatment with the BRAFi PXL4032 on sensitive BRAF mutant melanoma cell lines induced senescent resistant clones that portrayed a stem cell-like phenotype and had an aberrant expression of multiple epigenetic modifiers such as HDAC6." (PMID 34944799, 2021). "Therefore, as a key signaling node, RICTOR contributes to BRAF-dependent melanoma development and resistance to therapy and, as such, is a valuable therapeutic target in melanoma." (PMID 34680615, 2021). "Finally, we tested the anti-tumorigenic effect of CRO15 in mice injected with A375 R melanoma cells presenting acquired resistance to the BRAF inhibitor PLX4032." (PMID 33431809, 2021). "In addition, the composition of BRAF and MEK inhibitors is reasonable for melanoma patients with BRAF V600 mutations but has limited efficacy for patients with rectal cancer." (PMID 34692498, 2021).
melanoma (continued). "The first BRAF inhibitor in melanomas was vemurafenib, which demonstrated efficacy in BRAFV600E/K mutant melanomas in the BRIM-3 phase 3 randomized clinical trial that demonstrated the overall survival (OS) advantage compared to dacarbazine, with an objective response rate (ORR) of 48%." (PMID 34831002, 2021). "Moreover, HA15 also exhibited strong efficacy in xenograft mouse models with melanoma cells either sensitive or resistant to BRAF inhibitors." (PMID 34065438, 2021). "BRAF mutant melanoma patients also have the option of combination BRAF and MEK inhibitors." (PMID 34677256, 2021). "In RAS-mutated melanoma, PKA regulates the MAPK/ERK signaling by switching BRAF to RAF-1 signaling." (PMID 33396632, 2020). "Following this line of research, we decided to investigate if OLEO could be able to inhibit the metabolism of BRAF melanoma cells, that are usually glycolysis-addicted." (PMID 32013090, 2020). "Indeed, 28% of all melanoma cases have mutations in the NRAS gene, being after BRAF mutations the second most frequent oncogenic alteration in this type of cancer." (PMID 33072757, 2020). "In BRAF-mutant melanoma cells inhibition of BRAF induces concomitant glucose uptake reduction." (PMID 32509589, 2020). "We also identify multiple novel drug combinations that may overcome BRAF inhibitor-resistance in melanoma." (PMID 31857724, 2020). "Additional studies are warranted to define the place of MEKi and ICI in BRAF-WT melanoma." (PMID 32585901, 2020). "Hence, in this review, we highlighted the important role of miRNAs not only in the current treatments of melanoma metastasis but also their involvement in drug resistance to BRAF and MEK inhibitors, and their role as prognostic factors (biomarkers)." (PMID 32013263, 2020). "Recently, the introduction of molecularly targeted therapies and immunotherapy has given hope to patients with advanced melanoma, and several trials are evaluating the effect of BRAF inhibitors and immune checkpoint inhibitors in patients with brain metastases." (PMID 31915016, 2020). "Additionally, a large subset of melanomas is characterized by high levels of PGC1-α and increased OXPHOS metabolism independently of BRAF mutational status." (PMID 32528879, 2020). "In our study, we found the combinations with synergistic inhibitory effect on two cell lines (one melanoma and one colon) harboring BRAF and concomitant PI3K pathway mutations but not all the cell lines in this mutational group." (PMID 33081092, 2020). "Food and Drug Administration (FDA) approved Nivolumab as a single agent for patients with BRAF V600 wild-type unresectable or metastatic melanoma and in combination with Ipilimumab for patients with melanoma with lymph node involvement or metastatic disease who have undergone complete resection." (PMID 32671117, 2020). "These combinations kill melanoma cells, regardless of their mutation status in BRAF or NRAS, likely because MCL1 and BCLXL are downstream of these common mutations." (PMID 32513939, 2020). "Consequently, BRAF testing is considered mandatory in patients with advanced (unresectable or metastatic) melanomas stage III or stage IV, and is highly recommended in high-risk resected disease stage IIC." (PMID 36046072, 2020). "To determine whether BETi treatment may contribute to improved therapeutic outcomes in BRAF-mutant melanoma in vivo, we compared the triple combination of BRAFi/MEKi/BETi with BRAF/MEK targeting in xenograft models." (PMID 31932756, 2020). "Triple wild-type melanomas (BRAF, RAS, and NF1 wild type) typically lack a UV signature." (PMID 32123303, 2020). "Though V600E mutation in BRAF gene has been previously reported to confer a fragmented mitochondrial phenotype and drug resistance to melanoma, the underlying mechanism/s is not clear, especially with respect to form function relationship." (PMID 33738242, 2020).
melanoma (continued). "For example, the activation of ERK signaling in melanoma when treated with BRAF inhibitors may lead to paradoxical activation of CRAF3." (PMID 32487991, 2020). "We wished to extend this observation by ascertaining whether DUSP4 or ETV4 might also influence the response of wild-type BRAF melanoma cells to MEK inhibition." (PMID 31839677, 2020). "BRAF is a member of the Raf kinase family, and oncogenic mutations in BRAF activate the mitogen-activating protein kinase (MAPK)/extracellular signal-related kinase (ERK) kinase (MEK)→ERK signaling pathway, which is required for melanoma growth and metastasis." (PMID 32371878, 2020). "Unlike cutaneous malignant melanomas, the prevalence of BRAF mutations in mucosal malignant melanoma is usually accompanied by c-kit mutations." (PMID 32642388, 2020). "This work investigates the metabolic characteristics and vulnerabilities of acquired resistance to vemurafenib in three generated BRAF-mutant human melanoma cell clones, analysing metabolic profiles, gene and protein expression in baseline and nutrient withdrawal conditions." (PMID 31819183, 2020). "In addition to being highly immunogenic, another defining characteristic of melanoma is constitutive activation of the MAPK pathway, via BRAF V600 mutations." (PMID 32913556, 2020). "Our results show that LNPs encapsulating combinations of the two oncosuppressor miRNAs are highly efficient in impairing melanoma cell proliferation and viability, affect key signaling pathways involved in melanoma cell survival, and potentiate the efficacy of drugs inhibiting BRAF and MEK." (PMID 32178301, 2020). "These four compounds alone or in synergistic combinations may provide a basis for enhanced immune recognition and may aid design novel therapeutic approaches for patients with BRAF mutant melanoma resistant to immunotherapy." (PMID 32231230, 2020). "While only melanoma cells bearing the BRAF V600E mutation responded in our assays to pyridinyl imidazole compounds by ERK signaling inhibition, the cellular vacuolization, and delocalization of mTOR kinase was observed in both NRAS- and BRAF-mutant cells." (PMID 32531927, 2020). "In conclusion, the activity of MEK inhibition (specifically, trametinib) outside the narrow window of patients with melanoma and class 2 mutations, does not appear robust in cancers harboring non-V600 BRAF mutations." (PMID 33216832, 2020). "For instance, melanoma cells upon BRAF inhibition (BRAFi) can exhibit enhanced OXPHOS." (PMID 32923395, 2020). "BRAF mutations are not sufficient for melanoma development or progression, as they are already also found in benign nevi." (PMID 32605090, 2020). "Notably, ShcD silencing sensitizes BRAF-mutant melanoma cells to targeted therapy, suggesting that the regulation of ShcD expression influences both the cell motility and drug sensitivity of melanoma cells." (PMID 33202906, 2020). "This combination of BH3 mimetics offers a potential therapeutic strategy for the treatment of advanced melanomas, including those without BRAF hotspot mutations." (PMID 32764384, 2020). "We found comparable results for BRAF gene status in melanoma samples by two types of methodologies." (PMID 32054005, 2020). "Overall, knocking down the expression of AURKB could suppress both vemurafenib-sensitive and -resistant melanoma cell growth and induce apoptosis through the mediation of the BRAF/MEK/ERKs and PI3-K/AKT pathways." (PMID 32863956, 2020). "Beads, emulsion, amplification and magnetics (BEAMing) and droplet digital PCR (ddPCR), two PCR-based techniques, have very high sensitivity, but they are limited by the need for a specific gene target and hence used mostly in wild type melanoma for BRAF, NRAS or c-KIT." (PMID 33233603, 2020).
melanoma (continued). "Notably, we developed a dual-target inhibitor against both AURKB and BRAF V600E, which suppresses both drug-sensitive and -resistant melanoma development." (PMID 32863956, 2020). "The dual targeting of essential pro-growth pathways in melanoma cells indicates the potential for the development of BRAF inhibitors based on the pyridinyl imidazole core that could be less prone to the development of acquired drug resistance." (PMID 32531927, 2020). "These datasets are suitable for analysis of genes involved in cell viability and glycolysis in steady state conditions and following treatment with vemurafenib, as well as computational approaches to identify gene regulatory networks that mediate response to BRAF inhibition in melanoma." (PMID 33046726, 2020). "Of note, abemaciclib demonstrated to be particularly effective in BRAF resistant melanoma cells." (PMID 32850962, 2020). "Metastatic melanoma patients treated with BRAF and/or MEKis between March 1, 2012 and May 18, 2018 were included retrospectively (Lyon Sud University Hospital, Hospices Civils de Lyon)." (PMID 32056395, 2020). "Future in vitro studies should clarify if BRAF/TERT mutant melanoma cell lines, after exposure to MAPKi and to stimuli activating the TNFR superfamily, show different TERT expression and telomerase activity, as well as different telomere length based on TERTprom mutation type." (PMID 32290374, 2020). "Concerning ctDNA molecular features, mutations in the BRAF, NRAS, KIT and TERT genes are considered melanoma-driving mutations and their detection could help to adapt the strategy for patient monitoring." (PMID 32295074, 2020). "Furthermore, SHP-2 acts as an oncogene in BRAF wild-type (either NRAS mutant or wild-type) melanoma cells." (PMID 33003469, 2020). "Our recent results also reveal that a distinct SL profile, i.e., a tendency for increased very long-chain ceramide species, was observed in the plasma of patients with melanoma who achieve a response to a BRAF-targeted therapy as compared with patients with progressive disease." (PMID 32858889, 2020). "We show here that a low BRAF mRNA expression may explain a lower responsiveness to BRAF inhibitors in melanoma cell lines." (PMID 32393282, 2020). "Interestingly, PDK1 knockdown sensitizes BRAF-mutant melanoma to BRAF inhibitor treatment 132, suggesting the role of senescence PDK1-mediated drug resistance." (PMID 32483452, 2020). "This is also the case of target therapy in BRAF-mutant melanomas." (PMID 33202944, 2020). "Activating mutations of BRAF and NRAS are the most common mutations observed in melanoma." (PMID 32196516, 2020). "As such, pharmacological drugs capable of interfering with CDC42 activity could induce conformational alterations in the actin cytoskeleton, impairing the invasiveness of BRAF-resistant melanoma cells." (PMID 33072757, 2020). "The combination of BRAF and/or MEK inhibitors with anti-PD1 is a therapeutic alternative sometimes used in clinical practice in BRAF mutated or WT melanoma when no other approved therapeutic option or clinical trial is available." (PMID 32585901, 2020). "Using scRNA-seq analysis and cluster assessment (SAKE) to track melanoma cells that have developed resistance to BRAF inhibitors, several BRAF inhibitor resistance markers have been obtained, and new resistance markers have been identified in very few cell populations before using drug." (PMID 33614479, 2020). "We recently reported that BRAF-mutated SKMEL5 melanoma cells enter a non-quiescent “idling” population state upon long-term MAPKi treatment." (PMID 32923395, 2020). "The observation that BM perturbation was already observed after 2 weeks of culture could be due to the intrinsic invasion-related traits of the melanoma cell line used (SK-MEL-28), being BRAF/PTEN mutated and derived from a skin metastatic lesion." (PMID 32507967, 2020).
melanoma (continued). "Indeed, TTCC blockers reduce melanoma cell viability and migration/invasion in vitro and tumor growth in mice xenografts in both BRAF-inhibitor-sensitive and -resistant scenarios." (PMID 32046241, 2020). "In addition, as manipulation of the BRAF mutation was correlated in HIF-1α expression in vitro studies of melanoma cell lines and the thyroid cancer cell line (BCPAP), the link between BRAF mutation and Hif-1α expression is highly suspected." (PMID 32847004, 2020). "For instance, treatment of BRAF-mutant melanomas with BRAF inhibitor, vemurafenib, or with MEK inhibitor, selumetinib, leads to microphthalmia-associated transcription factor (MITF) signalling and elevated expression of the mitochondrial master regulator, PGC-1α." (PMID 33092283, 2020). "In another study of 127 melanomas, eight had MAP2K1 point mutations and two had MAP2K2 point mutations; these alterations were associated with constitutive ERK phosphorylation, and most co-occurred with either BRAF or NRAS mutation." (PMID 32483240, 2020). "The authors of this study reviewed the TCGA database and identified MAP2K1 alterations in 7% of melanomas, consisting mostly of point mutations with some amplifications and no in-frame deletions, with nearly all co-occurring with BRAF or NRAS mutations." (PMID 32483240, 2020). "However, one of the early BRAF inhibitors, sorafenib, demonstrated toxicity, including non-specific side effects, and resulted in low clinical responses in patients with melanoma." (PMID 32260561, 2020). "Even though COX-2 expression did not correlate with BRAF/NRAS mutation status, it seems that BRAF-mutated melanomas have an increased COX-2 and PD-L1 expression via IL-1 upregulation." (PMID 32296574, 2020). "Although it is well established that increased glycolysis and a dependency on the Warburg Effect are commonly observed in BRAF driven melanoma cells, recent studies on resistance to BRAF inhibitors in melanoma suggest a greater role of mitochondrial metabolism in a subset of cells." (PMID 32046099, 2020). "First, we have chosen a BRAF inhibitor, Dabrafenib (DAB), a drug already approved by the FDA in 2013 for the treatment of advanced metastatic melanoma bearing the mutated BRAF gene (BRAFV600E) found in ~70% of melanoma tumors." (PMID 32266211, 2020). "Interestingly, NRAS-mutant melanoma patients show worse survival, relapse rate and therapy response than patients with wild type NRAS or with BRAF mutations." (PMID 31906480, 2020). "BRAF mutations were more frequently identified in melanomas without chromic sun-induced damage (non-CSD), while RAS mutations were more likely observed in acral melanomas." (PMID 32083130, 2020). "In full concordance, Galectin-1 expression was also significantly increased in A375 and SK-MEL-28 melanoma cells that developed resistance in culture upon prolonged treatment with escalating concentrations of the BRAF inhibitor PLX-4720, thus recapitulating the process occurring in patients." (PMID 32784465, 2020). "Finally, combining MCL-1i with either BRAF or MEK inhibitors re-sensitized melanoma cells and enhanced tumor growth inhibition in vivo." (PMID 33308268, 2020). "Together, these data indicate that use of an intermittent BETi schedule may be tolerable and enhances the effects of BRAFi/MEKi in BRAF-mutant melanoma." (PMID 31932756, 2020). "Administration of the BRAF small molecule inhibitor PLX4720 had similar effects in a murine model of melanoma; PLX4720 reduced tumor growth by promoting the formation of a more immune stimulatory microenvironment correlated with a reduced accumulation of CD11b+/GR-1+ myeloid cells." (PMID 32656079, 2020). "Of the 24 patients with melanoma, 22 had no BRAF mutations, 1 patient with cutaneous melanoma had a BRAF mutation, and 1 patient with mucosal melanoma was not evaluated for BRAF mutations." (PMID 32297948, 2020).